MRPS14 (mitochondrial ribosomal protein S14)
Synonyms: MRP-S14; S14mt; HSMRPS14; uS14m; COXPD38; DJ262D12.2
Tractability: Small molecule: a structure with a bound ligand is known. PROTAC: its protein half-life has been measured.
Gene: Protein-coding gene on chromosome 1 (175,010,789 to 175,023,432, reverse strand). Ensembl gene ENSG00000120333.
Subcellular location: Mitochondrion
Subcellular location (Human Protein Atlas): Mitochondria; Nuclear membrane
Pathways (Reactome):
Metabolism of proteins: Mitochondrial ribosome-associated quality control; Mitochondrial translation elongation; Mitochondrial translation initiation; Mitochondrial translation termination
Gene Ontology:
Molecular function: protein binding; RNA binding; structural constituent of ribosome
Biological process: mitochondrial translation; translation
Cellular component: mitochondrial small ribosomal subunit; mitochondrion; mitochondrial inner membrane; mitochondrial ribosome; ribosome
Genetic constraint (gnomAD): Loss-of-function variants: 14 observed, 17.31 expected, observed/expected ratio (o/e) 0.81, 90% interval 0.53 to 1.26. The upper end of that interval is the gene's LOEUF score, 1.26, which puts it in group 5 of 6, group 1 being the genes least tolerant of losing a copy. Missense variants: 162 observed, 184.92 expected, observed/expected ratio (o/e) 0.88, 90% interval 0.77 to 1. Synonymous variants: 54 observed, 65.8 expected, observed/expected ratio (o/e) 0.82, 90% interval 0.66 to 1.03.
Gene-disease validity (ClinGen):
ClinGen rates the evidence that MRPS14 causes each of these diseases.
mitochondrial disease (autosomal recessive): Limited.
Homologues: Orthologues: macaque MRPS14 (99% identical), chimpanzee MRPS14 (91% identical), dog MRPS14 (90% identical), guinea pig MRPS14 (88% identical), mouse Mrps14 (87% identical), pig MRPS14 (86% identical), rat Mrps14 (79% identical), tropical clawed frog mrps14 (77% identical), zebrafish mrps14 (73% identical), Drosophila melanogaster mRpS14 (59% identical), Caenorhabditis elegans mrps-14 (36% identical).
Diseases named in the same sentence as MRPS14 in open-access papers:
MRPS14 is named in the same sentence as 13 diseases in open-access papers, as found by Europe PMC text mining. Sharing a sentence is not in itself a finding about the gene and the disease. The quoted sentences say what the papers report.
hepatocellular carcinoma (1 paper, 2025). A malignant tumor that arises from hepatocytes. "In addition, MRPS14, as part of the mitochondrial ribosome, has been reported to be significantly overexpressed in hepatocellular carcinoma, suggesting a potential role in tumor metabolic reprogramming and as a diagnostic biomarker." (PMID 40863222, 2025).
hypertrophic cardiomyopathy (1 paper, 2025). A condition in which the myocardium is hypertrophied without an obvious cause. "A previous report noted Subject‐R108C possessed homozygous MRPS14 variants (c.322C>T; p.R108C) that were associated with diffuse hypotonia, hypertrophic cardiomyopathy, cognitive disability, motor delays, along with elevated serum lactate and alanine levels (no neuroimaging results were reported)." (PMID 40317698, 2025).
melanoma (1 paper, 2024). A malignant, usually aggressive tumor composed of atypical, neoplastic melanocytes. "We previously performed unbiased proteomic analysis on the mitochondria of AP-4-139B treated melanoma cells and identified novel HSP70 client proteins including MRPS14 and NDUFA6." (PMID 38802657, 2024).
schizophrenia (1 paper, 2014). A major psychotic disorder characterized by abnormalities in the perception or expression of reality. "When we compared our data with the previous genome-wide DNA methylation study using CpG-island microarrays, we found one common gene, MRPS14 (mitochondrial ribosomal protein S14), which showed significantly higher- DNA methylation changes in schizophrenia in both studies." (PMID 25206360, 2014).
cancer (1 paper, 2024). A tumor composed of atypical neoplastic, often pleomorphic cells that invade other tissues. "Interestingly, VER-155008 and the HSP90 inhibitor 17-AAG did not cause a reduction in MRPS14, consistent with the notion that HSP70 and HSP90 have some non-overlapping roles in proteostasis and cancer." (PMID 38802657, 2024).
mitochondrial disease (1 paper, 2022). "Mitochondrial disease-causing mutations were found in thirteen small ribosomal subunit mitoribosomal proteins (MRPS1, MRPS2, MRPS6, MRPS7, MRPS9, MRPS11, MRPS14, MRPS16; MRPS22, MRPS23, MRPS25, MRPS34, MRPS39) and four large ribosomal mitochondrial proteins (MRPL3, MRPL12, MRPL24, MRPL44)." (PMID 36140315, 2022).
MRPS14 also shares sentences with these, for which no sentence is quoted: cardiac disease (1 paper); cardiomyopathy (1); chronic kidney disease (1); cognitive delay (1); kidney disease (1); Leigh syndrome (1); tumor (1).